CTNNB1 (catenin beta 1)
Diseases named in the same sentence as CTNNB1 in open-access papers (continued):
Sharing a sentence is not in itself a finding about the gene and the disease.
liver cancer (continued). "RBM24 inhibits nuclear translocation of CTNNB1 in liver cancer cells." (PMID 34804951, 2021). "In liver cancer, the phosphorylation sites of β-catenin are absent due to mutations to the CTNNB1 gene, leading to the constitutive activation of Wnt/β-catenin signaling." (PMID 32486480, 2020). "First, we generate precise in-frame deletions in the gene encoding β‐catenin (CTNNB1) that result in proliferation independent of Wnt-stimuli, mimicking a mechanism of the development of liver cancer." (PMID 33097693, 2020). "To validate our tumour findings, we looked at the effects of HGF treatment on β-catenin and Y654-β-catenin in two liver cancer cell lines, with and without CTNNB1 mutations." (PMID 21992464, 2011). "Zonal positioning in the liver determines whether the CTNNB1 oncogene can induce liver cancer." (PMID 41261129, 2026). "70% hepatic cancer without CTNNB1 mutation may contribute to the low response rate of genetically unclassified HCC to DFO." (PMID 36703130, 2023). "Moreover, WES in the HCC tissue revealed somatic mutations CTNNB1 p.S33P and NFE2L2 p.D27_L30delID that could better explain the rapid development of liver cancer." (PMID 35884482, 2022). "In liver cancer, the MIDN/CTNNB1/MMP9 axis promotes progression through inducing a suppressive tumour immune microenvironment." (PMID 40111059, 2025). "The expression differences of the six Hub genes C3, CTNNB1, CYBC1, DNASE1L3, IRAK1, and SERPINE1 between human liver cancer cell lines and normal liver cell lines are statistically significant." (PMID 39055701, 2024). "The cell lines showed relatively low expression compared with normal liver cells, while CTNNB1, CYBC1, IRAK1, and SERPINE1 showed relatively high expression in HCCLM3 and 97H liver cancer cell lines compared with normal liver cells." (PMID 39055701, 2024). "Among the six hub genes, C3 and DNASE1L3 are relatively low expressed in HCCLM3 and 97H liver cancer cell lines, while CTNNB1, CYBC1, IRAK1, and SERPINE1 are relatively overexpressed in liver cancer cell lines." (PMID 39055701, 2024). "In summary, seven of the genes (VEGFA, CTNNB1, SPP1, PPARG, RAC1, HSP90AA1, and LGALS3) were highly unregulated in patients with liver cancer." (PMID 35069936, 2022). "STAT3 and CASP3 were dysregulated in liver cancer; however, NOTCH1 and CTNNB1 were related to pancreatic cancer." (PMID 35154607, 2021). "STAT3 and CASP3 were determined as specific hub nodes related to liver cancer, while NOTCH1 and CTNNB1 were characterized as the specific hubs of pancreatic cancer." (PMID 35154607, 2021). "Genomics studies indicated positive CTNNB-1 & IDH potentials in HC & IC target therapies and gene target therapies can improve prognosis of liver cancer." (PMID 33585001, 2020). "Mutations of HCC in the Wnt/β-catenin pathway frequently occur in HCC patients (~30% in CTNNB1 and ~10% in AXIN1) as well as multiple liver cancer cell lines." (PMID 31861402, 2019). "Although activated β-catenin signaling is required for hepatic APC knockout mice to develop liver cancer, mice did not developed liver tumors 6 m after hepatic Ctnnb1 exon 3 deletion." (PMID 36122209, 2022).
liver cancer (continued). "Potential mechanisms underlying the ARID2-CTNNB1 and ARID1A-AXIN1 associations in liver cancer have not been explored in depth, perhaps because these genes are less commonly altered in HCC (~10%) than TERT or CTNNB1." (PMID 34439356, 2021). "Another limitation of the present study is that the difference in Wnt/CTNNB1 mutations, apart from TERT promoter mutations, could not be investigated according to the etiology of liver cancer." (PMID 35306637, 2022).
colon carcinoma (107 papers, 2009 to 2026). "The S37 residue in CTNNB1 is a phosphorylation site and mutations have been found in colon cancers and melanoma." (PMID 38408048, 2024). "HNF4α and p-S133-CREB1 were significantly enriched at the promoter of Ctnnb1 in Apc mutation induced colon cancer tissues." (PMID 39320349, 2024). "Human colon cancers that lack APC mutations frequently have activating mutations in CTNNB1 (β-catenin) that prevent its phosphorylation by GSK-3, demonstrating a key epistatic relationship between APC and CTNNB1/β-catenin." (PMID 37759479, 2023). "In contrast to that, colonic tumors displayed various degrees of positivity for nuclear β-catenin (n = 10) and mutations of CTNNB1 (n = 4)." (PMID 34885050, 2021). "Although somatic mutations in CTNNB1 occur frequently in colon cancer, germline mutations have been less implicated in hereditary CRC." (PMID 34549727, 2021). "The FDA have already approved celecoxib for increased degradation of CTNNB1 gene mutations (β-catenin oncoprotein), frequently observed in colon cancer cells, and for reducing the number of colorectal polyps in patients with familial adenomatous polyposis." (PMID 33922284, 2021). "Accordingly, Wnt ‘super-activation’ by GSK3β inhibition (i.e., Chiron) in the APC/CTNNB1-mutated colon cancer cell lines results in a significant expansion of EpCAMlo cells and increased ZEB1 expression." (PMID 34036938, 2021). "Using cBioPortal, we queried the TCGA (PanCancer Atlas) dataset for expression of Wnt target genes in colon cancers with various categories of APC or CTNNB1 mutations." (PMID 32751567, 2020). "On the other hand, mutations of the CTNNB1 have been associated with other malignant tumors, such as melanoma, renal cell carcinoma, hepatocarcinoma, medulloblastoma, colon cancer, lung cancer, and ovarian cancer, among others." (PMID 31266530, 2019). "Most colon cancers are associated with mutations in APC or CTNNB1, and ~90% of colon cancers are associated with defects in the canonical Wnt signaling pathway." (PMID 30996256, 2019). "In our patient no pathogenic variants in the APC gene were found, but an identical activating CTNNB1 variant was present in both ovary and colon tumors." (PMID 29124495, 2018). "On the other hand activating CTNNB1 pathogenic variants are often found in colon cancer associated with DNA mismatch repair deficiency." (PMID 29124495, 2018). "Mutated APC gene is common in colon cancer, so aberrant activation of Wnt-CTNNB1 signaling pathway results in its progression." (PMID 29094602, 2018). "Greater than 90% of colon carcinomas contain inactivating mutations in the APC gene or activating mutations in the beta-catenin gene (CTNNB1)." (PMID 27999207, 2017). "In fact, Pyrvinium pamoate, an anti-helminth drug, was shown to decrease PYGO2 protein levels in colon cancer cells lines with Apc and Ctnnb1 mutations, and in ApcMin/+ mice." (PMID 27811361, 2016). "The Wnt pathway is often deregulated in colon cancer as a result of activating mutations in beta-catenin (CTNNB1) or inactivating mutations in adenomatous polyposis coli (APC), which is a negative regulator of beta-catenin." (PMID 26646695, 2015). "Mutations in APC or CTNNB1 are highly frequent in colon cancer and cause aberrant stabilization of CTNNB1, which activates the transcription of Wnt target genes by binding to chromatin via the TCF/LEF transcription factors." (PMID 24651522, 2014). "Previously, we demonstrated that DMH-induced colon cancers, beside mutations in Ctnnb1 (coding for β-catenin) and Kras, carry single-nucleotide mutations in Apc with a frequency of about 30%." (PMID 20459814, 2010). "We have recently reported that frizzled-7 (FZD7), 1 of 10 members of the FZD gene family, is predominantly expressed in colon cancer cells and is implicated in canonical Wnt signalling in colon cancer cells with APC or CTNNB1 mutations." (PMID 19773752, 2009).
colon carcinoma (continued). "To understand the transcriptional mechanism underlying the induction of colon cancer stemness, we constructed TetOff cells that conditionally expressed an artificially-designed microRNA (amiRNA or amiR) targeting the open reading frame of CTNNB1." (PMID 38182897, 2024). "Somatic mutations of CTNNB1 were exclusively detected in colonic carcinomas (p = 0.15)." (PMID 34885050, 2021). "However, no mutations were detected in either APC or KRAS, suggesting that mutated CTNNB1 is the driver in colon cancer development induced by PhIP/DSS." (PMID 34488905, 2021). "Ctnnb1 overexpression in an invasion front is a hallmark of colon cancer." (PMID 33396408, 2020). "As CTNNB1 variants are very rare in colon carcinomas, this might suggest the ovarian tumor as the primary origin." (PMID 29124495, 2018). "Additionally, mutations in the β-Catenin gene CTNNB1 were found in colon cancer leading to the constitutive activation of β-Catenin/LEF/TCF-dependent canonical signaling." (PMID 22685558, 2012). "Second, ACLY binds to the CTNNB1 gene, which encodes β‐catenin 1 protein, to form and promote complex transport from the cytosol into the nucleus, further increasing the CTNNB1 gene's transcriptional activity and resulting in the migration and invasion of colon cancer." (PMID 39584783, 2024). "However, recent findings revealed that Wnt ligands or inhibitors could affect the growth and survival of colon cancer cells in spite of the presence of APC or CTNNB1 mutations." (PMID 19773752, 2009). "In colon cancer, differentially-spliced 3UI transcripts are enriched in the Wnt signalling pathway, with CTNNB1 showing the greatest increase in splicing." (PMID 40716781, 2025). "For example, MINCR uses miR-708-5p to upregulate CTNNB1 and activate the Wnt/β-catenin pathway, thereby promoting colon cancer development." (PMID 38714724, 2024). "In 3 human colon cancer cell lines, siRNA knockdown of β-catenin (CTNNB1) dose-dependently reduced ZNF277 protein expression." (PMID 35015732, 2022). "In colon cancer, RSPO2 and RSPO3 gene fusions have been proposed to potentiate Wnt/β‐catenin signaling, providing a mutational alternative for classical APC and CTNNB1 mutations." (PMID 36106661, 2022). "More than 90% of the cases of sporadic colonic tumors harbor mutations in the core pathway components APC and/or β-catenin (CTNNB1)." (PMID 34849464, 2021). "A connection of tumors with colon inflammation is supported by the fact that the mutational landscape of inflammation-induced colon cancer differs from the majority of sporadic colon tumors, which typically harbor mutations in APC or Ctnnb1." (PMID 34849464, 2021). "CTNNB1 mutation was more frequent in endometrial cancer (16%), HCC (12%), or colon cancer (6%) than NSCLC (3%)." (PMID 34298845, 2021). "The aberrant WNT/CTNNB1 pathway in colon cancer always induces CIN, so the complete opposite relationship between CTNNB1 mutation and CIN in EC is confusing and interesting." (PMID 33110489, 2020). "ACLY also facilitates colon cancer cell metastasis, and high expression levels of ACLY and Catenin β1 (CTNNB1) protein were positively correlated with metastasis of colon cancer." (PMID 33194695, 2020). "Colon cancers frequently harbor truncating mutations to APC that yield proteins with impeded function in degrading β-catenin; or oncogenic mutations to the CTNNB1 gene that remove the destruction complex phosphorylation sites in the N-terminus of β-catenin." (PMID 32486480, 2020). "We wonder if ACLY affects the WNT/CTNNB1 signaling pathway, especially CTNNB1, in colon cancer metastasis." (PMID 31511060, 2019). "Since ~90% of colon cancers are associated with defects in the canonical Wnt signaling pathway, we selected colon cancer cell lines HCT116 and DLD-1 with mutations in APC and CTNNB1, respectively." (PMID 30996256, 2019). "The finding that the ACLY and CTNNB1 synergistically promote colon cancer metastasis led us to further examine their relationship." (PMID 31511060, 2019).
colon carcinoma (continued). "We analyzed the correlation between ACLY and CTNNB1 protein in 78 colon cancer patients by Pearson correlation." (PMID 31511060, 2019). "These factors are required for growth of organoids derived from healthy tissue but are dispensable for the growth of colon tumor organoids because these harbor mutations (APC, CTNNB1 (β-catenin), or AXIN) that activate Wnt signaling independently of ligands." (PMID 31752287, 2019). "Blocking β-catenin/TCF4 signaling using FH535 and CTNNB1-specific small interfering RNA decreased DCLK1 expression in HCT116 human colon cancer cells." (PMID 29254234, 2017). "Pygo2 failed to suppress Sox9 overexpression in Apc LOF, and only partially reduced elevated Sox9 in colon tumors and Ctnnb1 GOF mice." (PMID 27811361, 2016). "We analyzed chemically induced colon tumor development and conditional intestine specific mouse models harboring either Apc loss-of-function (LOF) or Ctnnb1 gain-of-function (ß-catenin GOF)." (PMID 27811361, 2016). "Several mouse models of Apc LOF and Ctnnb1 GOF were engineered that mimic the different stages of human colon cancer development." (PMID 27811361, 2016). "These included a colon cancer cell line with a gain-of-function mutation in CTNNB1 (HCT116) and two colon cancer cell lines with APC loss-of-function mutations (DLD1 and SW480)." (PMID 26528816, 2015). "We also uncovered a novel feed-forward mechanism where β-catenin protein stabilization and β-catenin/TCF transcription appear critical in regulating Ctnnb1/CTNNB1 transcription in the setting of Apc inactivation in mouse colon and human colon cancer cells." (PMID 26528816, 2015). "The active β-catenin protein pool was highly sensitive to CTNNB1 transcript levels in colon cancer cells." (PMID 26528816, 2015). "At 7 days after DOX-induction of the CTNNB1 shRNAs, in the three colon cancer cell lines, we found moderate (HCT116) to dramatic (DLD1 and SW480) decreases in the active pool of β-catenin protein with only modest changes in total β-catenin protein levels." (PMID 26528816, 2015). "Despite the significant correlation between chromatin binding and gene expression regulation, our work uncovers a small number of genes as direct, functional CTNNB1 targets in SW480 colon cancer cells." (PMID 24651522, 2014). "This analysis revealed a striking enrichment of the CTNNB1 target signature in colon cancer samples compared to normal colon tissues (NES = 2.01, FDR q-value = 0.0)." (PMID 24651522, 2014). "Our unbiased genome-scale screening for CTNNB1 target genes combining ChIP-seq and microarray analyses provides an important resource for colon cancer research." (PMID 24651522, 2014). "Our data provide a genome-wide view of chromatin occupancy and gene regulation of Wnt/CTNNB1 signaling in colon cancer cells." (PMID 24651522, 2014). "Notably, mutations in the cancer-associated genes KRAS G12D (spontaneous thymic T lymphoma) and Ctnnb1 G34E (AOM-induced colon cancer) were detected in two of the four tumors." (PMID 40734673, 2025). "Moreover, they are relatively highly expressed and/or have positive correlation with CTNNB1’s expression in colon cancer samples." (PMID 39320349, 2024). "CTNNB1 expression was recovered by siNCKAP1 in TGFβ1-treated colon cancer cells." (PMID 36639705, 2023). "While we anticipated detecting genes previously implicated in colon cancer, the relative relationship to changes in CHRM1 expression suggests a common relationship between the concurrent changes observed in CHRM1 and APC/CTNNB1, and these downstream β-catenin target genes." (PMID 35370785, 2022).